IL1B (interleukin 1 beta)
Diseases named in the same sentence as IL1B in open-access papers (continued):
Sharing a sentence is not in itself a finding about the gene and the disease.
heart failure (continued). "Moreover, TNF-α and IL-1β contribute to cardiac hypertrophy, forming another risk factor for heart failure." (PMID 38270118, 2023). "To test the second hypothesis, we determined whether MI-derived systemic inflammation and induction of IL-1β might play a causal role in mediating the deterioration of the vascular niche in post-MI heart failure." (PMID 34172720, 2021). "Interestingly, in experimental mice harboring Tet2 deletion, myeloid Tet2 deficiency accelerated heart failure through the IL-1β/NLRP3 inflammasome." (PMID 31032261, 2019). "In addition, TNF-α and IL-1β induce cardiomyocyte hypertrophy, which is another independent risk factor of heart failure." (PMID 29511093, 2018). "The release of IL-1β results in widespread inflammation, leading to death of cardiomyocytes, progressive loss of viable contractile tissue, and development of cardiomyopathy and heart failure." (PMID 28232838, 2017). "The inflammatory mechanisms that induce instability in atherosclerotic plaques—especially NLRP3 activation, IL-1β signaling, and endothelial dysfunction—are also central to myocardial remodeling and heart failure." (PMID 40564905, 2025). "taVNS has been shown to suppress pro-inflammatory cytokines such as TNF-α and IL-1β, thereby mitigating the chronic low-grade inflammation commonly observed in heart failure." (PMID 41584276, 2025). "Since 1990, studies have confirmed elevated levels of various inflammatory mediators, including TNF-α, IL-6, IL-1β, IL-18, and immune antigens, in the plasma of heart failure patients." (PMID 40671145, 2025). "And the increase of IL-1β expression is more evident in heart failure, in addition, transgenic mice overexpressing IL-1β had cardiomyocyte hypertrophy and increased expression of ANP and β-MHC." (PMID 38172711, 2024). "Many of the involved inflammatory markers, such as IL-6, CRP, TNF-α, IL-1β, and macrophage inhibitory factor (MIF), have been associated with post-MI hypertrophy, remodeling, persistent systolic dysfunction, heart failure, and mortality." (PMID 38558749, 2024). "In the pathophysiology of heart failure, previous data demonstrated the critical roles of active IL-1β and IL-18." (PMID 38750444, 2024). "IL-1β increased bone marrow hematopoietic stem cell proliferation and leukocyte production after AMI in ApoE knockout mice, and anti-IL-1β treatment not only reduced this effect but also diminished post-AMI heart failure." (PMID 38256155, 2024). "The pro‐inflammatory cytokine IL‐1β contributes to myocardial hypertrophy and heart failure via cardiomyocyte hypertrophy induction and cardiac fibroblasts and immune cell activation." (PMID 39604027, 2024). "In this study, the active compounds of SGC were found to bind IL-1β for the treatment of heart failure." (PMID 38579077, 2024). "Canakinumab, conversely, demonstrated the ability to block NLRP3 inflammasome and IL-1β activations, highlighting IL-1-targeted therapy potential in preventing the recurrence of atherosclerotic thrombotic events and heart failure happening." (PMID 38650918, 2024). "Supporting IL1βs candidacy as an immunotherapeutic target, the phase 3 CANTOS trial, which tested the IL1β inhibitor canakinumab as a treatment for heart failure, demonstrated a greater than 50% reduction of death from all cancers." (PMID 39353903, 2024). "We found that WNK1 inhibition alleviated SARS-2-S-aggravated heart failure and reduced serum cTnT and IL-1β levels." (PMID 39102426, 2024). "IL-10 can also reduce proinflammatory cytokines such as TNF-α, IL-1β, and IL-6, as well as cardiac contractility in heart failure." (PMID 39200761, 2024). "For example, we found that HF-induced lung inflammation, fibrosis, and vessel remodeling were significantly attenuated by induction of endogenous Tregs, or administration of IL-1β blocking antibodies in mice with existing heart failure." (PMID 36860846, 2023).
heart failure (continued). "Cytokines, TNF-α, IL-1β, and IL-6, were found to be elevated in patients with heart failure, and their higher levels appear to be directly related to LVEF dysfunction." (PMID 35997998, 2023). "In mouse models of heart failure with hematopoietic or myeloid TET2 deficiency, IL-1β/NLRP3 inflammasome inhibitor ameliorated heart failure." (PMID 37928907, 2023). "In patients with heart failure symptoms, there is a correlation between circulating IL-1β levels and the incidence of AF." (PMID 37581942, 2023). "Canakinumab, a monoclonal antibody against IL-1B reduced heart failure rates, by possibly reducing myocardial remodeling." (PMID 37492439, 2023). "Recent studies have found that treatment with Ginaton alleviated renal interstitial fibrosis through the TGF-β pathway and that Ginaton also reduced TNF-α, IL-1β, and 5-hydroxytryptamine levels in the hippocampus of mice with heart failure." (PMID 36992835, 2023). "The inflammasome exerts an inflammatory effect by regulating the release of proinflammatory cytokines including IL-1β and IL-18, contributing to cardiomyocyte apoptosis and dysfunction, and leading to ventricular remodeling and heart failure." (PMID 36704451, 2022). "Increase in IL-1β+ inflammatory M1-like macrophage is also reported in TAC mice further suggesting its role in heart failure and cardiac remodeling." (PMID 35371099, 2022). "The pro-inflammatory cytokines TNFα, IL-1β and IL-6 are all involved in the inflammatory response related to the pathogenesis of heart failure." (PMID 36278179, 2022). "Circulating levels of cytokines: IL-1β, TNFα, IL-10, IL6, IL-8 and IL-12 were determined and investigated regarding their association with hemodynamic parameters, clinical signs of heart failure and outcome." (PMID 36014020, 2022). "This is likely caused by the influence of TET2 deficiency on the IL-1β/NLRP3 inflammatory pathway, as treatment with an NLRP3 inflammation inhibitor protected against the development of heart failure." (PMID 35872888, 2022). "For example, Il1b blockade has been shown to diminish adverse cardiac events and heart failure progression." (PMID 35411847, 2022). "In cardiovascular diseases, the production of various inflammatory cytokines, including TNF-α, IL-1β, and IL-6, leads to tissue damage, promoting atherosclerotic plaque formation, reduced vascular function, and progression of heart failure." (PMID 35431967, 2022). "Increase of CCL5 serum levels was also observed in patients with severe congestive heart failure, whereas upregulation of IL-1β exhibited a significant increase in 1-year mortality in the patients with heart failure." (PMID 34925046, 2021). "Upregulated genes from state 13 (post-MI heart failure enriched) revealed activation of Wnt and NF-κB signaling pathways, which are downstream of IL-1β." (PMID 34172720, 2021). "Conversely, inhibition of IL-1β signalling limits post-infarct heart failure by improving short-term cardiac function and reducing long-term remodelling and endothelial dysfunction." (PMID 34199975, 2021). "It is also worth noting that the caspase-1 downstream inflammatory cytokines, IL-1β and IL-18, accelerate the transition from cardiac remodeling to heart failure and thus are expected to be potential drug targets for heart failure." (PMID 33842546, 2021). "Serum levels of cytokines interleukin 1 beta ( IL-1β) and interleukin 33 (IL-33) are highly abnormal in heart failure and remain elevated after mechanical circulatory support (MCS)." (PMID 34768376, 2021).
heart failure (continued). "Analysis of transcript expression in the isolated hearts revealed that transcript expression of the proinflammatory cytokines Il6 and Il1b and the heart failure markers Anf and Bnp were significantly lower in Ccr2-KO mice." (PMID 34315245, 2021). "The in vivo study also had shown that Tet2 deficiency in hematopoietic cells is associated with greater cardiac dysfunction in murine models of heart failure as a result of elevated IL-1β signaling." (PMID 32377298, 2020). "Recent research proved that Canakinumab, as an IL‐1β inhibitor, provided a novel approach to treat heart failure post‐MI." (PMID 33084169, 2020). "Preclinical research and clinical trials validated the role of IL-1α in the initiation of post-MI inflammation and the role of IL-1β in adverse cardiac remodeling and heart failure." (PMID 33488934, 2020). "IL-1β is another potential cytokine target for the treatment of heart failure due to its up-regulation in heart failure, role in pro-inflammatory responses and positive benefits from IL-1β inhibition in preclinical trials." (PMID 33041853, 2020). "Preclinical studies have shown that anti-IL-1β therapy reduced post MI hematopoiesis and leukocytosis, enhanced inflammation resolution in the infarct, and ameliorated post-MI heart failure." (PMID 31032261, 2019). "So far, it has been found that inflammatory cytokines associated with the heart failure mechanism include TNF-α, IL-6, IL-8, IL-10, IL-1α, IL-1β, IL-2, TGF-β, and IFN-γ." (PMID 31275453, 2019). "Pro-inflammatory cytokines including TNF, IL-1β, and IL-6 are upregulated with decreased heart function, and are activated earlier in heart failure than the classic neurohormones." (PMID 29900007, 2018). "The levels of inflammatory cytokines (tumour necrosis factor-α [TNF-α], interleukin (IL)-1β, and IL-6) are increased in patients with heart failure." (PMID 29511093, 2018). "For instance, the levels of serum cytokines such as TNF-α, IL-6, and IL-1β are related to the severity of heart failure." (PMID 29511093, 2018). "High levels of proinflammatory cytokines, including TNF-α, IL-6, IL-1β, and IL-2, have a profound effect on pathogenesis and prognosis in heart failure." (PMID 29201273, 2017). "Compared to cartilage, HIF-2α regulated by IL-1β in cardiac myocytes play a role in the adaptation of the cardiac myocytes during heart failure ameliorating cardiac function." (PMID 29263346, 2017). "Serum concentrations of TNF-α, IL-1β and IL-6 were increased along with the severity of heart failure and the decrease of SNAQ scores as well." (PMID 29155861, 2017). "Actually, previous several studies suggested that brain IL-1β is increased in heart failure, and are involved in the mechanisms of sympathoexcitation." (PMID 23874864, 2013). "This is supported by the finding that levels of proinflammatory cytokines, including tumor necrosis factor (TNF)-α, interleukin (IL)-6 and IL-1β, increase during heart failure." (PMID 22569420, 2012). "Elevated TLR4 expression on mast cells and macrophages in the spleen and heart of CVB3 infected males not only increases acute myocarditis but induces expression of the profibrotic cytokine IL-1β resulting in cardiac dilatation and heart failure later." (PMID 21338512, 2011). "TNF-α and IL-1β: For some time the cytokines tumor necrosis factor (TNF)-α and IL-1β have been known to contribute to heart failure by inducing hypertrophy and/ or apoptosis of cardiac myocytes." (PMID 23675015, 2007). "Canakinumab (an anti IL-1β monoclonal antibody) was related to a dose-dependent reduction in heart failure hospitalizations and a composite of hospitalizations and HF-related mortality in a sub-analysis of the CANTOS trial but there was no distinction between HFrEF and HFpEF in that study." (PMID 41154649, 2025).
heart failure (continued). "On the other hand, IL-1β becomes the main chemical messenger during the later phases, leading to the demise of heart muscle cells, negative changes in the structure of the heart, and, ultimately, heart failure." (PMID 39844544, 2025). "NR treatment has been shown to reduce mitochondrial ROS production and inhibit the expression of proinflammatory factors, such as NLRP3 inflammatory vesicles and IL-1β and IL-18, as well as enhance mitochondrial respiration, which is beneficial for patients with heart failure." (PMID 40507126, 2025). "Patients with heart failure often have an inflammatory response, and inflammatory markers such as high-sensitivity C-reactive protein (hs-CRP), interleukin-1β (IL-1β), and interleukin-6 (IL-6) play important roles in the occurrence and development of heart failure." (PMID 41333015, 2025). "Treatment with anti-IL-1β antibodies has proved effective in heart failure models." (PMID 40360833, 2025). "For example, the release of S100A8/A9 from neutrophils during AMI can activate NLRP3 inflammatory vesicles, release IL‐1β, and stimulate granule formation in the bone marrow, resulting in neutrophil accumulation and ultimately poor myocardial remodelling and heart failure." (PMID 39087342, 2024). "Previous studies have revealed that inhibiting NLRP3 inflammasome activation in macrophages and thereby attenuating myocardial IL‐1β and IL‐18 levels effectively ameliorates myocardial ischemic injury and pressure overload‐induced heart failure and cardiac remodeling." (PMID 39604027, 2024). "In 2019, the Canakinumab Anti-Inflammatory Thrombosis Outcomes Study (CANTOS) findings showed that anti-cytokine therapy with a monoclonal antibody against IL-1β improved heart failure outcomes in patients with myocardial infarction with or without established heart failure." (PMID 36882679, 2023). "Furthermore, in murine models of heart failure with TET2 deficiency in hematopoietic cells, cardiac function worsened due to the elevation of IL-1β/NLRP3 inflammasome, and the models responded better to IL-1β/NLRP3 inflammasome inhibition." (PMID 37928907, 2023). "It was established that cytokines such as TNF-α, IL-1β, and IL-6 play an important role in the development of heart failure in several clinical scenarios, and some attempts were even made to regulate their effects on heart tissue, yet no conclusive treatment proposals were established." (PMID 35269577, 2022). "The levels of TNF-α and IL-7 were significantly higher in the saliva of patients with heart failure and normal saliva secretion compared to the controls, as was the content of IL-1β, TNF-α and IL-7 in the saliva of patients in the study group with hyposalivation compared to the control group." (PMID 36300113, 2022). "Blocking IL-1β might benefit patients with IBD by preventing cardiac remodeling that could lead to heart failure." (PMID 34543287, 2021). "A recent subgroup analysis of the CANTOS (Canakinumab Anti-inflammatory Thrombosis Outcome Study) trial showed that IL-1β-targeting therapy may decrease heart failure-related hospitalization and mortality." (PMID 35224023, 2021). "Therapeutically, administration of IL-1β-inhibiting agents (canakinumab, rilnacept, anakinra) result in a significantly lower rate of recurrent cardiovascular events and prevent future hospitalisation for heart failure." (PMID 34685553, 2021). "IL-1β is a crucial cytokine promoting the inflammatory reaction in heart failure." (PMID 34210954, 2021). "Moreover, in the CANTOS trial, administration of canakinumab (a monoclonal antibody targeting IL-1β) prevented the recurrence of ischemic events, reduced heart failure-related hospitalizations and mortality in patients with prior AMI." (PMID 34289931, 2021). "Pro-inflammatory cytokines, such as IL-1β, IL-6 and IL-13, play a significant role in regulating the progression from adaptive hypertrophy to heart failure." (PMID 31333486, 2019).
heart failure (continued). "Additionally, multiple studies have shown high levels of pro-inflammatory cytokines such as TNF-α, IL-6, and IL-1β in the peripheral circulation and heart of cardiac failure patients." (PMID 30558188, 2018). "Increased levels of IL-1β and IL-6 in RVs from SuH mice indicate the installation of a pro-inflammatory environment in the myocardium, and it has been described that these cytokines are involved with development of heart failure." (PMID 30574088, 2018). "Besides, in conditions where IL-1β and other cytokines levels are increased, such as after myocardial infraction and during progression of heart failure, elevated BNP plasma levels have been found." (PMID 28331244, 2017). "Interestingly, ADAMTS4 synthesis in macrophages increases in response to tumor necrosis factor (TNF)-α and interleukin (IL)-1β, cytokines which are found increased in the myocardium of heart failure patients, suggesting a role in heart failure development." (PMID 24595230, 2014). "On the other hand, the CANTOS trial has shown that the inhibition of IL-1b with canakinumab was followed by a significant trend for a dose-dependent reduction in the incidence of the composite endpoint of hospitalization for heart failure and heart failure-related mortality." (PMID 36661914, 2023). "NLRP3 inflammasome sets off the maturation of proinflammatory cytokines (IL-1β and IL-18) to initiate the inflammatory response and plays a key role in modulating chronic inflammation, altering the physiological adaptation of cardiomyocyte and leading to heart failure progression." (PMID 36661914, 2023). "In addition, SGLT2 inhibitors have been reported to benefit heart failure patients through IL-1β and/or NLRP3 inflammasome mechanisms, and may be used for immune modulation." (PMID 35997820, 2022). "In that case, inducing pro-IL-1β degradation in cardiac cells may limit subsequent inflammatory responses to cardiac tissue damage and hence serve as a cardio protective prophylactic intervention in patients with ischemic heart disease or heart failure." (PMID 31244838, 2019). "Therefore, we assume that the suppressive effect of MSC on NLRP3 inflammasome activation and IL-1β secretion by macrophages could be beneficial in viral myocarditis preventing disease progression to cardiac dilatation and heart failure." (PMID 29434214, 2018). "IL-1β is a potent pro-inflammatory cytokine, which induces the synthesis and expression of several hundreds of secondary inflammatory mediators and it is a key mediator of the systemic inflammatory response in heart failure, having a direct cardio-depressive effect." (PMID 29434214, 2018). "IL-1β has been demonstrated to be significantly related to infarction and left ventricular function after MI, and inhibited IL-1β expression could prevent heart failure after MI." (PMID 25202335, 2014). "Interestingly, Agrawal discovered that macrophage-mediated IL-1β partially regulates cardiac remodeling in an animal model of heart failure with preserved ejection fraction (HFpEF)-PH.This indicates that IL-1β from myeloid cells may be associated with the prognosis of PAH." (PMID 39979525, 2025). "Compared with HF group, IL-1β, IL-6 and TNF-α inflammatory factors in blood of rabbits with heart failure were decreased in different degrees after administration of dapagliflozin, and there were significant differences (P<0.05)." (PMID 39874368, 2025). "Dapagliflozin increased serum GSH-Px and SOD levels and decreased IL-1β, IL-6, TNF-α and MDA levels (P < 0.05) in a rabbit model of heart failure." (PMID 39874368, 2025). "In the heart failure group, NLRP3, TXNIP, Caspase-1, and IL-1β protein expressions were up-regulated, and aerobic exercise and SKQ1 down-regulated NLRP3, TXNIP, Caspase-1, and IL-1β protein expressions." (PMID 40076760, 2025).